FOXO1 (forkhead box O1)
Diseases named in the same sentence as FOXO1 in open-access papers (continued):
Sharing a sentence is not in itself a finding about the gene and the disease.
rheumatoid arthritis (13 papers, 2013 to 2024). A chronic, systemic autoimmune disorder characterized by inflammation in the synovial membranes and articular surfaces. "Various chronic inflammatory diseases, such as rheumatoid arthritis and pulmonary hypertension, are linked to deregulation of FoxO1-mediated signalling in certain cell populations." (PMID 35447890, 2022). "However, continuously active FOXO1 overexpression induces apoptosis associated with the altered expression of genes regulating cell cycle and survival in rheumatoid arthritis fibroblast-like synoviocytes." (PMID 33540675, 2021). "Using rheumatoid arthritis as an example of T cell mediated disease, we demonstrate interactions of expression quantitative trait loci with target genes, and confirm assigned genes or show complex interactions for 20% of disease associated loci, including FOXO1, which we confirm using CRISPR/Cas9." (PMID 32879318, 2020). "However, rapid downregulation of FoxO1 in rheumatoid arthritis fibroblast-like synoviocytes in response to IL-1β or PDGF stimulation is independent of Akt and results from accelerated c-Jun N-terminal kinase (JNK)-mediated degradation of FoxO1 mRNA." (PMID 35153742, 2021). "The 3′ intronic region of COG6 contains a number of SNPs associated with rheumatoid arthritis (RA) and juvenile idiopathic arthritis (JIA) which exhibited robust interactions with FOXO1, located over 1 Mb away." (PMID 35377406, 2022). "In addition, loss of FOXO proteins may be a potential etiology for systemic lupus erythematosus (SLE) and rheumatoid arthritis, since FOXO1 gene transcript levels are downregulated in peripheral blood mononuclear cellsof these patients." (PMID 32309538, 2013). "Inactivation of FOXO3 in T lymphocytes, as well as inactivation of FOXO1 and FOXO4 in synovial macrophages in patients with rheumatoid arthritis and osteoarthritis result in inflammatory cell activation." (PMID 32309538, 2013). "FOXO1 emerges as a critical downstream element of MST1, contributing to the regulatory mechanisms governing dsDNA-induced migration and invasion of RA FLSs, thereby enhancing our comprehension of the intricate signaling dynamics in the pathogenesis of rheumatoid arthritis." (PMID 38765007, 2024).
autoimmune disease (12 papers, 2015 to 2025). A disorder resulting from loss of function or tissue destruction of an organ or multiple organs, arising from humoral or cellular immune responses of the individual to their own tissue constituents. "Regulatory T cells that are deficient in FoxO1 are pro-inflammatory and develop autoimmune diseases." (PMID 37987301, 2023). "Collectively, our findings suggest that GLK-IKKβ-FoxO1 signaling in T cells suppresses regulatory T cells, leading to enhanced susceptibility to autoimmune diseases." (PMID 35966593, 2022). "Mice that lack FoxO1 in Treg cells (FoxP3-cre FoxO1fl/fl) mice exhibit severe autoimmune disease that is reminiscent of the disease found in FoxP3-deficient scurfy mice." (PMID 28267764, 2017). "STX8 and YES1 are implicated in T-cell activation, MAP4K5, RRM2B, FOXO1, ERBB2IP and INPPL1 can promote inflammation and KIM1, MVK and BANK1 have been associated with autoimmune diseases." (PMID 40247373, 2025). "In this study, we found that the RING finger protein 213 (RNF213) specifically promoted regulatory T (Treg) cell differentiation in CD4+ T cells and attenuated autoimmune disease development in an FOXO1-dependent manner." (PMID 39013878, 2024). "Besides, RNF213 interacts with FOXO1 (forkhead box protein O1) and facilitates the nuclear translocation of FOXO1 through K63-linked ubiquitination, thereby specifically promoting the differentiation of Treg cells and attenuating the development of autoimmune diseases." (PMID 40040717, 2025).
B-cell lymphoma (12 papers, 2014 to 2025). "Our data underlined the key role of multiple amino-acid residues of the forkhead domain in FOXO1 transcriptional activity and revealed a new type of FOXO1 loss-of-function mutations in B-cell lymphoma." (PMID 35079069, 2022). "Consistent with our findings, somatic missense FOXO1 mutations that target its AKT recognition motif have been recurrently identified in a significant fraction of germinal center origin of B cell lymphomas, including DLBCL, follicular lymphomas, and BL." (PMID 36282572, 2022). "The antitumor effect of FOXO1 activation was also shown in different B cell lymphomas, moreover, for some of them we have provided evidence for a Goldilocks-like (too little is bad as well as too much) behavior of FOXOs." (PMID 31557894, 2019). "TG101348 upregulates FOXO1 mRNA and protein expression in mediastinal B cell lymphoma cell lines MedB-1 and U2940 and inhibit the growth of mediastinal B cell lymphoma." (PMID 25869210, 2015). "As primary mediastinal B cell lymphoma (PMBL) has similarities with the cHL transcription program we investigated FOXO1 expression in this entity." (PMID 24977668, 2014). "Interestingly, the classical loss-of-function alterations seen in tumor-suppressor genes, such as frameshifts, premature stop codons or gene deletions, were rarely reported in the FOXO1 gene in B-cell lymphoma." (PMID 35079069, 2022). "Therefore, FoxO1 functions as tumor suppressor in various solid tumors and B cell lymphomas, including DLBCL." (PMID 32711549, 2020). "Although downregulation of the DZ program by FOXO1 knockdown in a MYC-driven mouse B cell lymphoma model that harbored a constitutively active version of the PI3K catalytic subunit has been recently reported, the repertoire of repressed genes was different from what we obtained in human cell lines." (PMID 31557894, 2019). "After coculture with FOXO1 mRNA-loaded nanoparticles, CAR-T cells exhibited and increased proportion of Tcms and enhanced antitumor efficacy against B cell lymphoma." (PMID 40693464, 2025). "In the study, we found that the FOXO1 gene was remarkably upregulated, while the FOXO4 gene was decreased in DLBC, which belongs to B-cell lymphoma." (PMID 36292640, 2022). "Given that genetic and pharmacological activation of FOXO1 induce apoptosis in different B cell lymphomas, we overexpressed an AKT-resistant inducible version of FOXO1 (FOXO1(3A)ER) in BL-41 and Namalwa BL cell lines." (PMID 31557894, 2019).
Cachexia (12 papers, 2015 to 2025). Severe weight loss, wasting of muscle, loss of appetite, and general debility related to a chronic disease. "Interestingly, many of the cachexia associated genes such as FOXO1, FOXO3, SIRT1, SMAD3 and FABP3 were identified in age related gene expression in similar direction." (PMID 33923976, 2021). "Importantly, FoxO1 is consistently identified as a cachexia‐associated gene increased in muscle of cancer patients, and we show that increased levels of FoxP1 are also associated with cachexia in cancer patients." (PMID 33527776, 2021). "Differential expression of cachexia-related signaling pathways, such as FoxO1/MuRF1/Atrogin-1, at different time-points throughout the disease course, would be of special interest." (PMID 38473431, 2024). "A total of 340 genes from muscle, including several known genes for cachexia such as FOXO1, FOXO3, PIK3RI, GLUL were correlated with CWLG." (PMID 33923976, 2021). "As expected, Walker 256 tumour growth led to muscle function decline, cachexia manifestation symptoms, muscle fibre cross-section area reduction, and classical muscle protein degradation pathway activation, with upregulation of FoxO1, MuRF-1, and 20S proteins." (PMID 34943780, 2021). "We found genes commonly identified in animal models of cachexia, such as FOXO1, FOXO3, IL6R, ZIP14 and PIK3R1, manifested in two independent muscle human datasets." (PMID 33923976, 2021). "Paradoxically, KD did not reverse the increased expression of atrophy markers Trim63, Foxo1 and Fbxo32 in gastrocnemius muscle, which suggests that ketones exert pro‐anabolic effects even in the presence of increased catabolism in cachexia." (PMID 38632714, 2024). "Notably, expression of genes involved in the regulation of metabolic activities, including Pik3r1, Pdk4, Foxo1, Rorc and Lpin1, increased in type IIb myonuclei upon cachexia." (PMID 39001644, 2024). "Xu and colleagues verified that the miRNA-486 decreases FoxO1 protein expression and promotes FoxO1 phosphorylation to suppress E3 ubiquitin ligases, presenting an excellent candidate for future studies on the mechanisms of regulation of muscle atrophy by miRNAs in cachexia." (PMID 26504359, 2015). "Gene-expression analysis by qPCR in different skeletal muscles showed increased expression of atrophy-related genes (MAFbx/Atrogin-1, Trim63/MuRF-1, Foxo-1) and the pro-inflammatory gene TNF-α, also known as cachectin, as additional sign of cachexia." (PMID 35013221, 2022). "Interestingly, the downregulated genes in muscle ECs of B16F10-cachexia mice were enriched for multiple cofactors of the transcriptional coactivator peroxisome proliferator-activated receptor (PPAR)γ coactivator 1α (PGC1α), such as Nrf1, PPARδ, Mef2, Hnf4 and forkhead box O1 (FOXO1)." (PMID 40419762, 2025).
diffuse large B-cell lymphoma (12 papers, 2015 to 2025). "In diffuse large B cell lymphoma, FoxO1 mutations with both activating and inactivating character have been observed." (PMID 39533662, 2025). "Somatic point mutations of the FOXO1 transcription factor were reported in non-Hodgkin lymphoma including diffuse large B-cell lymphoma, follicular lymphoma and Burkitt lymphoma." (PMID 35079069, 2022). "In diffuse large B-cell lymphoma, FOXO1 mutations occur in almost 10% of cases and are associated with decreased survival in patients." (PMID 31767615, 2019). "In addition, single-nucleotide somatic mutations in FOXO1, leading to over-activation of FOXO1, are frequently found in follicular lymphomas and diffuse large B-cell lymphomas." (PMID 38519029, 2024). "Previous studies have reported that mutations affecting residues M1 (R19-L27) in diffuse large B-cell lymphoma (DLBCL) lead to the loss of the AKT recognition motif or abnormal nuclear localization of FOXO1, correlating with poorer prognoses." (PMID 41372946, 2025). "In other B cell malignancies, such as chronic lymphocytic leukemia, diffuse large B cell lymphoma or mantle cell lymphoma, FoxO1 can exhibit functions that diverge from those seen in their healthy counterparts." (PMID 39533662, 2025). "TXN curtails p300-mediated FOXO1 acetylation and its nuclear translocation in response to oxidative stress, thus attenuates FOXO1 transcriptional activity toward genes involved in apoptosis and cell cycle inhibition in diffuse large B-cell lymphomas." (PMID 27835585, 2016). "However, in diffuse large B cell lymphoma, malignant cells utilize FoxO1 in contradictory ways with recurrent presence of both activating and inactivating mutations." (PMID 39533662, 2025). "Interestingly, both belong to the FOXO family, and compared with normal samples, FOXO1 was highly expressed in lymphoid neoplasm diffuse large B-cell lymphoma (DLBC); however, FOXO4 was down expression in DLBC." (PMID 36292640, 2022). "In diffuse large B‐cell lymphoma, knocking out TXN can promote p300‐mediated acetylation of FoxO1 and expression of FoxO1, thereby increasing FoxO1 transcription of apoptosis genes and cell cycle inhibitory genes." (PMID 39778006, 2025). "The prognostic implications of miR-21, miR-17-92 and miR-155 were evaluated in diffuse large B-cell lymphoma (DLBCL) patients, and novel mechanism by which miR-21 contributes to the oncogenesis of DLBCL by regulating FOXO1 and PI3K/AKT/mTOR pathway was investigated." (PMID 25909227, 2015).
nonalcoholic steatohepatitis (12 papers, 2019 to 2025). "Inhibition of FOXO1 attenuates ER stress and necroptosis in a mouse model of non-alcoholic steatohepatitis." (PMID 32218743, 2020). "FoxO1 expression and activity have been reported to be increased in human steatohepatitis livers and are correlated with the severity of nonalcoholic steatohepatitis." (PMID 31246177, 2019). "Accordingly, in the context of nonalcoholic steatohepatitis (NASH), a systemic metabolic disease that causes liver damage, acetate promotes the auto-aggressive phenotype of CXCR6+ CD8+ T cells sensitized by IL-15 signaling and low FOXO1 expression." (PMID 38411744, 2024). "For example, salvianolic acid B could reduce oxidative stress response by regulating Sirt3/FoxO1 signaling pathway and play a role in the treatment of nonalcoholic steatohepatitis." (PMID 35959265, 2022). "For instance, in a nonalcoholic steatohepatitis (NASH) rat model induced by a high-fat diet, the inhibition of PI3K leads to FOXO1 activation, which plays a crucial role in hepatic stellate cell (HSC)-induced hepatic fibrosis." (PMID 38891336, 2024). "In addition, FOXO1 expression differs in precancerous lesions from two conditions that lead to HCC, non-alcoholic steatohepatitis (NASH) and alcoholic steatohepatitis (ASH), which also reflects different tumorigenic rates for ASH and NASH." (PMID 34123834, 2021).
osteoarthritis (12 papers, 2015 to 2025). A noninflammatory degenerative joint disease occurring chiefly in older persons, characterized by degeneration of the articular cartilage, hypertrophy of bone at the margins and changes in the synovial membrane. "Additionally, early-onset osteoarthritis was observed in FoxO1 or FoxO3-deficient mice, whereas FoxO1 shielded chondrocytes from oxidative stress and promoted the overexpression of genes related to autophagy and proteoglycan 4, a crucial joint lubricant." (PMID 38987770, 2024). "This study provides valuable insights into the role of the IRS2/AKT/FOXO1 axis in osteoarthritis (OA), uncovering a mechanism by which FOXO1 is regulated through autophagy in chondrocytes, independent of acetylation." (PMID 41013182, 2025). "Studies have also demonstrated that target regulating Foxo1 in chondrocytes can prevent osteoarthritis via autophagy." (PMID 37762015, 2023). "This review concluded that FoxO1, a forkhead O family protein, which is a decisive mediator of autophagy, facilitates the pathological process of osteoarthritis." (PMID 35560791, 2022). "Furthermore, FoxO1 is known to reduce oxidative stress in chondrocytes and increase the expression of autophagic genes, suggesting a protective role in the context of osteoarthritis." (PMID 40806700, 2025). "In addition, our enrichment analysis has clarified that FOXO1 is associated with the regulation of ECM-receptor interaction pathway, in line with evidence of osteoarthritis for the involvement of aberrant FOXO1 expression in ECM-receptor interaction pathway." (PMID 35154571, 2022). "For clinical relevance, we extended our analysis to published data from knee synovial tissues of osteoarthritis patients, 28 29 which similarly showed that THY1-PRG4+CLIC5+ FLS exhibited SOX5, FOXO1 and CREB5 regulon activity." (PMID 36414376, 2023). "Recent findings suggest that the FOXO1 gene is important in the survival of fibroblast-like synoviocytes (FLS) in RA18 and is hypermethylated in RA FLS compared with osteoarthritis FLS19, providing strong supporting functional evidence as to gene candidature." (PMID 26616563, 2015). "Interestingly, alterations in articular cartilage have been associated with the suppression of FoxO transcription factors, as mice lacking FoxO1 or FoxO3 show early-onset osteoarthritis." (PMID 40806700, 2025).
Alzheimer disease (11 papers, 2012 to 2024). A progressive, neurodegenerative disease characterized by loss of function and death of nerve cells in several areas of the brain leading to loss of cognitive function such as memory and language. "However, increased FoxO1 may mitigate Alzheimer’s disease, a neurodegenerative disease strongly associated with T2D." (PMID 37941908, 2023). "For example, neurodegenerative diseases like Alzheimer’s disease (AD), Huntington’s disease (HD), and Parkinson’s disease (PD) are worsened by T2D, and FoxO1 expression is elevated in each of these conditions." (PMID 37941908, 2023). "Aberrant APP signaling epistatically activates FOXO1 inducing cell death in Alzheimer’s disease (AD) mouse models." (PMID 29066835, 2017). "FoxO1 is an important target in the treatment of Alzheimer's disease (AD)." (PMID 36892036, 2024). "Therefore, the function of FoxO1 and FoxO3a has been investigated in animal models of Alzheimer's disease in detail." (PMID 22654904, 2012). "Additionally, several studies found that SIRT1/FoxO1 signaling could be activated by physical exercise to improve PINK1/PARKIN-mediated mitophagy in Alzheimer’s disease." (PMID 37629033, 2023). "To strengthen the specificity of FOXO1-mediated effects, we have made the comparative analysis using the APPswe/PS1dE9 (APP/PS1) mouse model of Alzheimer’s disease." (PMID 38556884, 2024). "In addition, physalin B is effective against Alzheimer’s disease through downregulation of β-amyloid (Aβ) secretion and beta-secretase 1 (BACE1) expression by activating forkhead box O1 (FoxO1) and inhibiting STAT3 phosphorylation." (PMID 35163960, 2022).